SOST (sclerostin)
Diseases named in the same sentence as SOST in open-access papers (continued):
Sharing a sentence is not in itself a finding about the gene and the disease.
osteoporosis (continued). "For example, sclerosteosis and van Buchem11,12 – two monogenic bone overgrowth diseases- are caused by rare loss of function mutations or the deletion of an enhancer element (ECR5) of SOST, and the osteoporosis-pseudoglioma syndrome is caused by rare loss of function mutations of LRP513." (PMID 30026596, 2018). "Collectively, these findings suggest that bone loss associated with steroid-induced osteoporosis is a consequence of sclerostin-mediated restriction of Wnt signaling, which may mechanistically facilitate glucocorticoid toxicity in bone." (PMID 28529816, 2017). "The findings were similar in patients with osteopenia (r = 0.631) and osteoporosis (r = 0.682), which suggested that IL-20 may be involved in osteoblastogenesis by regulating sclerostin, and associated with metabolic bone diseases." (PMID 27075747, 2016). "Their high efficiency to block sclerostin might facilitate the development of new drugs targeting diseases characterized by bone loss such as osteoporosis." (PMID 27558933, 2016). "The restricted expression of sclerostin to the skeleton and the lack of abnormalities in organs other than the skeleton in patients with sclerostin deficiency made this protein an attractive target for the development of a new bone forming therapy for the management of osteoporosis." (PMID 26892377, 2016). "Additionally, the collected data support the investigation of RANKL, OPG, and SOST as potential diagnostic markers for osteoporosis related to SM: these cytokines may serve as novel treatment targets in mastocytosis with bone implications." (PMID 40565113, 2025). "Interestingly, sclerostin deletion was associated with a marked loss of dexamethasone inhibition effect on bone formation suggesting that sclerostin was a key player in steroid-induced osteoporosis." (PMID 40146323, 2025). "Many studies have confirmed that sclerostin has been implicated in the pathogenesis of osteoporosis, so we speculate that sclerostin plays an important role in osteoporosis through the glucose metabolism pathway, which may promote the osteoporosis of morbidity in type 1 diabetes and type 2 diabetes." (PMID 39720253, 2024). "Increased SOST expression might therefore cause reciprocal effects: diminutive craniofacial and long bones with low bone density, corresponding to T21 phenotypes of short stature and early-onset osteoporosis-osteopenia (50% of individuals)." (PMID 38828726, 2024). "Therefore, sedentary SCI may be associated with high serum sclerostin levels that are related to osteoporosis." (PMID 35742035, 2022). "Studies have shown that targeting sclerostin with romozosumab, a sclerostin monoclonal antibody, is an effective strategy that increases bone mineral density and reduces fracture risk in postmenopausal women and patients with multiple myeloma with osteoporosis." (PMID 35208525, 2022). "Among them, bisphosphonates, denosumab, teriparatide and romosozumab (an sclerostin antibody) have a specific action on bone with a significant decrease in all types of fractures, but no extra skeletal beneficial effect on the medical conditions associated with the causes of osteoporosis." (PMID 34445256, 2021). "Therefore, the inhibition of sclerostin was proposed as a therapeutic approach in the treatment of bone loss, which led to the development and approval in the US and Europe of the monoclonal sclerostin-antibody Romosozumab for severe osteoporosis." (PMID 32668736, 2020). "SOST is an important player in the pathogenesis of osteoporosis; the finding that its expression is associated with DNA methylation could make it a useful biomarker of diagnosis of osteoporosis." (PMID 30729116, 2019). "Research in animals suggests that sclerostin may be a potential target for the treatment of conditions of characterized by low BMD and increased risk of fractures, such as osteoporosis, and sclerostin is being investigated as a treatment for post-menopausal osteoporosis." (PMID 30666305, 2018).
osteoporosis (continued). "Interestingly, small nuclear polymorphism in the regulator elements of the SOST gene could be linked to predisposition for osteoporosis." (PMID 24312339, 2013). "Evenity (romosozumab) is a humanized IgG2 monoclonal antibody targeting sclerostin, for the treatment of osteoporosis." (PMID 42098243, 2026). "Sarcopenia was defined based on grip strength and appendicular skeletal muscle mass (ASM), osteoporosis was diagnosed according to femoral T-scores, and serum sclerostin levels were measured using ELISA." (PMID 41594249, 2026). "This study explored the relationship between circulating sclerostin levels and two age-related musculoskeletal conditions—sarcopenia and osteoporosis—in postmenopausal women." (PMID 41594249, 2026). "Anabolic bone treatments are a new frontier: for example, romosozumab (an anti-sclerostin antibody) highly favors new bone formation and is approved for severe osteoporosis." (PMID 41496922, 2026). "In fact, the anti-sclerostin antibody (romosozumab) was approved to treat osteoporosis, and its strong bone-forming effect demonstrates the validity of targeting this network." (PMID 41495343, 2026). "Romosozumab, a monoclonal antibody targeting sclerostin, has shown clinical efficacy in improving bone mineral density (BMD) and reducing fracture risk in patients with osteoporosis." (PMID 41594249, 2026). "Sclerostin (SOST) is a key negative regulator of bone formation and an emerging biomarker associated not only with osteoporosis but also with chronic kidney disease." (PMID 41736700, 2026). "Romosozumab is a monoclonal antibody against sclerostin that initially exhibits potent anabolic effects in treating osteoporosis." (PMID 40827677, 2026). "These markers represent potential therapeutic targets, with anti-sclerostin antibodies already approved for osteoporosis treatment." (PMID 41367909, 2025). "During the differentiation and proliferation of osteoblasts and osteoclasts, the high expression of SOST can inhibit bone formation and contribute to osteoporosis and the bone metastasis of malignant tumors." (PMID 40563496, 2025). "Building upon our previous successes in addressing immune tolerance in osteoporosis vaccine development, we propose a novel vaccine strategy that integrates the SOST protein with a diphtheria toxin translocation domain (DTT) as an adjuvant scaffold." (PMID 41403949, 2025). "For example, in patients with osteoporosis, osteocyte-secreted Sclerostin can cross the blood–brain barrier, inhibit neuronal Wnt/β-catenin signaling, and promote β-amyloid (Aβ) accumulation, thus accelerating cognitive decline." (PMID 40417122, 2025). "Romosozumab, a sclerostin inhibitor FDA-approved for the treatment of osteoporosis in postmenopausal women, has potential efficacy in MM bone disease." (PMID 40862742, 2025). "The negative regulation of bone mass of sclerostin has made it a promising target for anti-osteoporosis drugs." (PMID 40307216, 2025). "Research findings based on the osteoporosis in female mice show that the miR-665/SOST axis plays a crucial role in regulating the phenotypes of bone marrow mesenchymal stem cells and the development of osteoporosis symptoms." (PMID 40443995, 2025). "In this study, we present an innovative osteoporosis vaccine targeting the SOST epitope (SOST131-163), which was identified through ROMO screening." (PMID 41403949, 2025). "These factors, in combination with sclerostin up-regulation resulting from reduced mechanical loading, contribute to a converging pathological process that promotes bone degradation in osteoporosis." (PMID 41377940, 2025). "Sales of sclerostin inhibitors also increased significantly (slope = +4.38, p = 0.0021, R2 = 0.927), reflecting the emerging role of anabolic agents in osteoporosis treatment." (PMID 40428763, 2025).
osteoporosis (continued). "The novel biochemical theory of modulating BRRS via tooth movement offers new clinical options for treating osteoporosis, including the use of sclerostin-inhibiting antibodies and intermittent periodontal PTHrP to promote bone apposition." (PMID 40115506, 2025). "Treatment with Romosozumab, a neutralizing antibody against Sclerostin, increases bone mass by uncoupling the transient activation of osteoblasts with the sustained inhibition of osteoclast activity in osteoporosis patients." (PMID 40004668, 2025). "Notable loci, including SOST and LRP5, have deepened our understanding of osteoporosis genetics and informed therapeutic advancements, such as sclerostin inhibitors and WNT modulators." (PMID 40411668, 2025). "Its encoded protein (sclerostin) is inhibited by romosozumab, a monoclonal anti-sclerostin antibody, used to increase bone mass and treat osteoporosis." (PMID 40205036, 2025). "A number of clinical trials are currently underway to explore the therapeutic efficacy of BDFs, particularly focusing on the inhibition of RANKL and Sclerostin in the management of osteoporosis as well as various other bone disorders." (PMID 40307216, 2025). "The risk factors agreed upon for osteoporosis in CKD included female sex, hyperphosphatemia, hyperparathyroidism, sclerostin overproduction, glucocorticoids usage, hyperprolactinemia, hypogonadism, and malnutrition." (PMID 40708576, 2025). "Osteoporosis is a systemic skeletal disorder marked by diminished osteoblast differentiation, primarily due to the overexpression of the SOST gene." (PMID 40605263, 2025). "Moving forward, it is vital that further studies concentrate on the targeted inhibition of sclerostin in bone specifically to develop effective treatments for osteoporosis while minimizing systemic adverse effects." (PMID 40307216, 2025). "Monogenic forms, often syndromic, were linked to mutations in genes such as COL1A1, COL1A2, and WNT1, whereas multifactorial osteoporosis, particularly postmenopausal, was associated with variants in LRP5, SOST, VDR, and other GWAS-identified loci." (PMID 40772209, 2025). "For osteoporosis, modulating the SOST gene enhances bone formation, while inhibiting RANKL reduces bone resorption, thereby increasing bone density and preventing fractures." (PMID 40255230, 2025). "Among them, romosozumab, an anti-sclerostin antibody, is a potent pharmacological tool to prevent fractures in osteoporosis patients." (PMID 39825110, 2025). "Future studies that examine the incidence of depression and cognitive aging among patients treated with monoclonal antibodies to SOST for osteoporosis will provide innovative insight into these potential relationships." (PMID 39286983, 2024). "In 2019, the European Medicines Agency approved romosozumab, an anti-sclerostin antibody, for osteoporosis treatment." (PMID 38679740, 2024). "SOST is a well-known Wnt antagonist in bone that is highly expressed by mature osteocytes and is the target of the most recently approved osteoporosis drug romozosumab." (PMID 39400554, 2024). "Patients with type 1 diabetes and type 2 diabetes are both more likely to suffer from osteoporosis, and serum sclerostin levels are elevated in osteoporosis." (PMID 39720253, 2024). "Sclerostin levels weresignificantly decreased in osteoporosis (4.62 ± 1.6 ng/mL) and osteopenia (4.92 ± 1.4 ng/mL) compared with controls(5.74 ± 1.3 ng/mL), (p < 0.0001)." (PMID 38352898, 2024). "For instance, a recent study found a positive correlation between sclerostin and Dkk1 expression in bone from postmenopausal women with osteoporosis and BMD, with their serum levels reflecting their bone levels." (PMID 38474734, 2024). "The importance of sclerostin to skeletal homeostasis is well-established, and romosozumab (anti-sclerostin monoclonal antibody) has emerged as a potent osteoanabolic agent in osteoporosis treatment." (PMID 39320468, 2024).
osteoporosis (continued). "It has been shown that inhibition of sclerostin affects osteoclast and bone resorption in animals with induced osteoporosis." (PMID 39581932, 2024). "Patients with osteopenia and osteoporosis have low circulating serum sclerostin levels and significantly decreased BMD." (PMID 38352898, 2024). "Sclerostin is a powerful protein molecules involved in bone metabolism and skeletal muscle regeneration, mainly related to osteoporosis." (PMID 39720253, 2024). "Omosozumab, a monoclonal antibody against SOST, has received approval and is now utilized in clinical management of osteoporosis." (PMID 39439909, 2024). "Sclerostin contributes to adult osteoporosis, and sclerostin antibody-based therapies have been developed." (PMID 39062269, 2024). "Elevated levels of sclerostin can hinder osteoblast activity, thus facilitating the progression of osteoporosis." (PMID 39767786, 2024). "It is known that alterations in the methylation profile of the SOST gene disrupt the transactivation of RUNX2 in postmenopausal osteoporosis patients and affect bone tissue metabolism." (PMID 39000419, 2024). "Monoclonal antibodies against beta-amyloid and tau for AD, as well as RANKL and sclerostin for osteoporosis, have displayed therapeutic potential." (PMID 38334917, 2024). "Romosozumab is a monoclonal antibody approved for osteoporosis which targets sclerostin, an endogenous inhibitor of Wnt/β-catenin pathway." (PMID 39104397, 2024). "Numerous clinical studies have also demonstrated that patients with osteoporosis exhibit elevated levels of serum sclerostin." (PMID 39720253, 2024). "While sclerostin’s original role prevents excess bone formation, in CKD patients, it is called calcification paradox of the sclerostin because it is pathologically increased along with an increase in osteoporosis." (PMID 38341544, 2024). "Secreted by osteocytes, sclerostin is negatively correlated with bone turnover and osteoporosis in post-menopausal women." (PMID 39339002, 2024). "Several large GWAS have investigated the genetics of osteoporosis, revealing BMD-associated genes, including ESR1, LRP4, ITGA1, LRP5, SOST, SPP1, TNFRSF11A (RANK), TNFRSF11 (RANKL), and TNFRSF11B (OPG)." (PMID 39769358, 2024). "Several therapeutics have emerged for the treatment of post-menopausal osteoporosis that target sclerostin." (PMID 39062269, 2024). "This will provide a basis for sclerostin as a new biomarker for diabetes-induced osteoporosis, as well as for potential therapeutic targets." (PMID 39720253, 2024). "Sclerostin, another inhibitor of the bone anabolic Wnt signaling pathway, is a target for romosozumab treatment against osteoporosis." (PMID 38791593, 2024). "Existing evidence suggests that sclerostin antibodies such as romosozumab reduce sclerostin expression, leading to improvement in osteoporosis." (PMID 39720253, 2024). "Romosozumab, a humanized monoclonal antibody used to treat osteoporosis, inhibits sclerostin, a molecule expressed by osteocytes and involved with inhibition of osteogenesis via Wnt/β-catenin pathway." (PMID 38285083, 2024). "In a cross-sectional study conducted by Ahmad, we learned that sclerostin was significantly higher in T2D compared to healthy people; Moreover, the incidence of osteopenia and osteoporosis in T2D is higher than that in the healthy people." (PMID 39720253, 2024). "Through literature review and previous research, we have learned that sclerostin plays an important role in the pathogenesis of osteoporosis, especially when accompanied by abnormal glucose metabolism." (PMID 39720253, 2024). "Romosozumab, a humanized neutralizing monoclonal antibody (anti-sclerostin), is an approved treatment for postmenopausal women with osteoporosis." (PMID 39125906, 2024). "The deficiency of LRP5 (loss of function) causes osteoporosis–pseudoglioma (OPPG), while the impaired SOST stimulates bone formation in mice and humans." (PMID 39125906, 2024).
osteoporosis (continued). "Clinically, the antiosteoporosis drug romosozumab, which antagonizes SOST, has demonstrated antiresorptive effects in postmenopausal women with osteoporosis." (PMID 39641271, 2024). "Meanwhile, romosozumab, an approved sclerostin antibody for osteoporosis, has also entered a phase 1 trial for OI." (PMID 37198232, 2023). "Compared with traditional anti-resorption drugs, anti-SOST antibodies, and anti-Dkk-1 antibodies can effectively increase bone formation and reverse the decline of bone mineral density in osteoporosis patients." (PMID 36979418, 2023). "As there are established treatments for osteoporosis using sclerostin inhibitor drugs, it would be interesting to further investigate their efficacy in hyperthyroidism for the reservation of bone mass." (PMID 36837860, 2023). "After SOST/sclerostin blockade, bone volume increases, and endophyte fixation improves in osteoporosis." (PMID 37121919, 2023). "The recognition of the clinical consequences of sclerostin absence stimulated the development of sclerostin inhibitors as a potential therapy for bone disorders characterized by excessive bone resorption, such as osteoporosis." (PMID 37108735, 2023). "The drug efficacy of anti‐SOST antibody, which is a newly developed osteoporosis drug for bone formation, was tested via β‐catenin translocation analysis, and the performance of the platform was evaluated using AI‐based deep learning analysis." (PMID 36684077, 2023). "This research revealed a notable augmentation in the SOST promoter’s methylation levels among individuals afflicted with osteoporosis." (PMID 37056287, 2023). "SHR-1222 is a novel humanized monoclonal antibody targeting sclerostin that was developed for the treatment of osteoporosis." (PMID 37091850, 2023). "To date, several genome-wide association studies (GWASs) have found hundreds of candidate genes associated with osteoporosis, including RANKL, SOST, ESR1, PTHLH, and DKK1." (PMID 37683138, 2023). "In contrast, the WNT signaling activator (the anti-sclerostin antibody EVENITY) is approved for osteoporosis." (PMID 36814601, 2023). "Notwithstanding that, romosozumab, a sclerostin inhibitor, yielded encouraging results in preventing and treating GC induced osteoporosis (GIOP) in RA patients corroborating our finding." (PMID 38022514, 2023). "Romosozumab is approved for osteoporosis and targets Sclerostin, thereby increasing WNT signaling in osteoblasts." (PMID 38203403, 2023). "Further studies also demonstrated that postmenopausal women with osteoporosis exhibit lower levels of sclerostin than healthy controls and an increase in circulating sclerostin levels after risedronate treatment in patients with osteoporosis." (PMID 36977715, 2023). "The inhibition of sclerostin is a therapeutic approach to increasing bone mineral density (BMD) and lowering fracture risk in patients with osteoporosis." (PMID 37096546, 2023). "A recently created anti-osteoporosis medication called Romosozumab, the first sclerostin inhibitor licensed by the U.S. FDA, targets sclerostin, has demonstrated remarkable effectiveness in treating postmenopausal osteoporosis." (PMID 37215218, 2023). "Both teriparatide and anti-sclerostin monoclonal antibody are treatment options for patients with concomitant HPP and osteoporosis and for those with atypical fractures caused by bisphosphonate use." (PMID 37249457, 2023). "The anti-sclerostin antibody romosozumab was approved by the European Medicines Agency (EMA) in 2019 for the treatment of osteoporosis." (PMID 37371669, 2023). "A previous study showed that DKK1 and SOST levels in the cortical bone matrix correlated positively with bone mass and strength in postmenopausal women with osteoporosis." (PMID 36768718, 2023). "In animal models of osteoporosis, inhibition of SOST by the monoclonal antibodies omosozumab and blosozumab induced osteoblast differentiation and new bone formation, normalized bone mass, and improved bone structure and strength." (PMID 36979418, 2023).